IGF2BP3 (insulin like growth factor 2 mRNA binding protein 3)
Diseases named in the same sentence as IGF2BP3 in open-access papers (continued):
Sharing a sentence is not in itself a finding about the gene and the disease.
cervical carcinoma (continued). "We believe that IGF2BP3 ubiquitination could be a good biomarker for cervical cancer." (PMID 37877353, 2023). "However, it remains unknown whether the oncogenic activity of IGF2BP3 is related to its ubiquitination in cervical cancer." (PMID 37877353, 2023). "IGF2BP3 regulated SCD mRNA m6A modifications via IGF2BP3–METTL14 complex, thereby enhancing cervical cancer proliferation, metastasis, and lipid metabolism." (PMID 40428320, 2025). "However, the mechanism by which IGF2BP3 regulates cervical cancer remains unclear." (PMID 38358034, 2024). "After the treatment of cervical cancer cells with ATL III, qRT–PCR results showed that both groups of cell lines showed significant reductions in the transcription levels of IGF2BP3 after drug intervention." (PMID 38358034, 2024). "The results of IHC revealed that the expression of IGF2BP3 protein in CIN III and cervical carcinoma tissues was increased compared to that in normal tissues." (PMID 38358034, 2024). "IGF2BP3 can accelerate the degradation of EIF4E-BP2 mRNA, thereby promoting the proliferation of cervical cancer cells." (PMID 34234866, 2021). "Consistently, IGF2BP3 and YTHDF1, the readers of PDK4 mRNA, significantly increased in cervical cancer tissues as compared with that in the normal control samples." (PMID 32444598, 2020). "We studied the mechanism of ATL III in cervical cancer cells, and according to the qRT–PCR results, ATL III downregulates IGF2BP3 in HeLa and SiHa cells, which indicates that IGF2BP3 may be a common target of ATL III in HeLa and SiHa cells." (PMID 38358034, 2024). "Additionally, IGF2BP3 mediates METTL3 to regulate the stability of RAB2B mRNA, thus promoting the proliferation of cervical cancer cells." (PMID 37298373, 2023). "KCNMB2-AS1 is significantly overexpressed in cervical cancer, and KCNMB2-AS1 evidently facilitates tumor growth by sponging miR-130b-5p and miR-4294 and then upregulating insulin like growth factor 2 mRNA binding protein 3 (IGF2BP3)." (PMID 34516362, 2021).
prostate carcinoma (21 papers, 2020 to 2025). A carcinoma that arises from epithelial cells of the prostate gland. "This suggests that IGF2BP3 is promising as a non-invasive diagnostic marker of prostate cancer." (PMID 37298373, 2023). "In prostate cancer, a circular RNA called hsa_cir_0003258 bound to IGF2BP3 in the cytoplasm, leading to increased stability of HDAC4 mRNA and promoting cancer metastasis." (PMID 38760723, 2024). "Specifically, circ-0003258 has been shown to promote prostate cancer metastasis by sponging miR-653-5p and interacting with IGF2BP3." (PMID 39030638, 2024). "In prostate cancer, hsa_circ_0003258 directly binds IGF2BP3 and enhances its function of stabilizing m6A-methylated HDAC4 transcript, contributing to EMT and metastasis by stimulating the MAPK signaling pathway." (PMID 37280679, 2023). "The role of IGF2BP3 in PCa is gradually being revealed, but its mechanism of action in prostate cancer needs further study." (PMID 37298373, 2023). "For instance, hsa_circ_0003258 promotes prostate cancer metastasis by complexing with IGF2BP3 and sponging miR-653-5p." (PMID 36028854, 2022). "Simultaneously, IGF2BP3 was identified as an independent prognostic indicator in renal papillary cell carcinoma, hematological malignancies, and prostate cancer." (PMID 35136045, 2022). "It was found that the expression of METTL14, IGF2BP3, HNRNPA2B1, and CNV of ALKBH5 were linked to the recurrence-free survival of prostate cancer." (PMID 34899855, 2021). "Less research has been conducted on how IGF2BP3 affects prostate cancer progression." (PMID 37298373, 2023). "Importantly, IGF2BP3, HNRNPA2B1, and METTL14 were significantly associated with RFS of prostate cancer in multivariable cox regression established on mRNA expression of m6A methylation regulators." (PMID 32710725, 2020). "Unlike the m6A modulators mentioned previously, IGF2BP3 has been proven to be secreted into serum and could be a promising diagnostic and prognostic marker of prostate cancer and renal cell carcinoma." (PMID 36891946, 2023). "Additionally, the interactions between Hsa_circ_0003258 and IGF2BP3 could promote prostate cancer metastasis and circ-0039411 could recruit IGF2BP3 to promote malignant behaviors of LUAD cells." (PMID 36139074, 2022). "IGF2BP3 is highly expressed in a variety of tumors including HCC, lung, and prostate cancers, and it helps maintain tumor cell growth, proliferation, invasion, and drug resistance through several oncogenic pathways." (PMID 36211823, 2022). "In the previous studies, IGF2BP3 was considered a poor prognostic factor for NSCLC, prostate cancer, and endocrine system tumours." (PMID 34802443, 2021). "To confirm our funding, we added critical clinical characteristics such as diagnosed age, GS, tumor T stage and N stage, the three m6A methylation regulators (IGF2BP3, HNRNPA2B1, and METTL14) were still remarkably related with prognosis of prostate cancer." (PMID 32710725, 2020). "We presented IGF2BP3, HNRNPA2B1 and METTL14 were significantly related to RFS of prostate cancer based on mRNA expression information, while in the CNV-based regression model, YTHDF2, FTO, and ALKBH5 were notably associated with prognosis of prostate cancer." (PMID 32710725, 2020). "Additionally, hsa_circ_0003258/IGF2BP3/HDAC4 and hsa_circ_0003258/miR-653-5p/ARHGAP5 crosstalk can promote prostate cancer progression." (PMID 37298373, 2023). "Similarly, IGF2BP3 (p < 0.05), HNRNPA2B1 (p < 0.05) and WTAP (p < 0.05) were significantly related to prostate cancer RFS in univariate cox regression analyses." (PMID 32710725, 2020).
Ewing sarcoma (18 papers, 2018 to 2026). A small round cell tumor that lacks morphologic, immunohistochemical, and electron microscopic evidence of neuroectodermal differentiation. "In Ewing sarcoma, IGF2BP3 loss promotes the downregulation of IGF1R and a decreased biological response to IGF1." (PMID 40442778, 2025). "Compensatory activation of the insulin receptor (IR) and its mitogenic ligand IGF2 is triggered in some Ewing sarcoma cells in response to IGF2BP3 mediated IGF1R loss." (PMID 40442778, 2025). "Interestingly, in Ewing sarcoma cell lines, IGF2BP3-mediated IGF1R loss is compensated by the activation of an IR-A/IGF2 autocrine loop, which determines higher sensitivity to the dual IGF1R/IR inhibitor OSI-906." (PMID 33673232, 2021). "The BET bromodomain inhibitor JQ1 has been shown to reduce IGF2BP3 expression in neonatal megakaryocytes and Ewing sarcoma cells." (PMID 40162116, 2025). "The RBP IGF2BP3 serves as a prognostic biomarker for patients with Ewing sarcoma where its high expression correlates with poor patient survival through increased metastasis." (PMID 40442778, 2025). "IGF2BP3 is expected to be one of the targets to inhibit the metastasis of Ewing sarcoma, but more research evidence is needed to support this." (PMID 37298373, 2023). "The BET inhibitor JQ1 inhibited mRNA and protein expression of the RNA-binding protein IGF2BP3 in Ewing sarcoma and B cell acute lymphoblastic leukemia." (PMID 34440844, 2021). "Accordingly, Ewing sarcoma cells with decreased expression of IGF2BP3 and the IGF1R, but increased compensatory expression of the IR, displayed higher sensitivity to OSI-906 compared to cells expressing high levels of IGF2BP3." (PMID 34440844, 2021). "In Ewing sarcoma, IGF2BP3 serves as an effective indicator of poor prognosis and predicts the recurrence of patients." (PMID 34026613, 2021). "Moreover, a recent study showed that the diazepine derivative JQ1 decreases IGF2BP3 expression, which in turn increases the survival rate of Ewing’s sarcoma patients." (PMID 40530014, 2025). "In 2018, a study found that IGF2BP3 is a tumor-promoting factor in Ewing sarcoma." (PMID 37298373, 2023). "Therefore, in this study, we investigated the value of IGF2BP3 as a novel regulator of the IGF system in Ewing sarcoma (ES), the second most frequent primary tumor of the bone affecting children and adolescents." (PMID 29731738, 2018). "EV-miRNA profiling revealed that IGF2BP3 silencing of Ewing’s sarcoma cells altered specific miRNAs associated with the PI3K/Akt pathway in recipient cells, including miR-223-3p which target IGF1R, a major driver of EWS aggressiveness and a previously reported target of IGF2BP3." (PMID 38730633, 2024). "In addition, inhibitors of bromodomain and extraterminal domain (BET) proteins, such as JQ1 or iBET, have been found to downregulate IGF2BP3 expression and its targets in Ewing sarcoma and B cell acute lymphoblastic leukemia, consequently attenuating tumor growth." (PMID 32010687, 2019). "Consistent with the findings in neonatal megakaryocytes and Ewing sarcoma, both JQ1 and dBET1 dose-dependently reduced IGF2BP3 protein levels in WaGa and MKL1 cells." (PMID 40162116, 2025). "HMGA2, IGF2BP2, IGF2BP3, and IGF2 were confirmed to be significantly overexpressed in CDS-derived cell lines compared with Ewing sarcoma–derived cell lines." (PMID 34903601, 2022). "At the preclinical level, expression levels of the RNA-binding protein IGF2BP3, in combination with the IGF1R/IR ratio, were suggested as putative predictor of response to linsitinib (OSI-906) in Ewing sarcoma cells." (PMID 34440844, 2021). "Consistently, as observed in Ewing sarcoma cells, the functions of IGF2BP3 can be limited by the mRNA expression of ABCF1, which is a partner transcript of IGF2BP3." (PMID 32010687, 2019).
Ewing sarcoma (continued). "Taking into account that IGF2BP3 sustains IGF1R expression as well, we can speculate that co-targeting the IGF axis and CXCR4 in Ewing sarcoma cells expressing high levels of IGF2BP3 might represent a valuable therapeutic option." (PMID 34440844, 2021). "We have very recently demonstrated that IGF2BP3 controls the expression of the chemokine receptor CXCR4 through post-transcriptional regulation of its functional partner CD164, thus promoting the motility of Ewing sarcoma cells toward the CXCR4-ligand CXCL12 under hypoxia conditions." (PMID 33673232, 2021). "qRT-PCR confirmed that CDS specimens exhibited significantly elevated expression of HMGA2, IGF2BP2, IGF2BP3, and IGF2, but not HMGA1, compared with Ewing sarcoma specimens." (PMID 34903601, 2022).
thyroid cancer (15 papers, 2016 to 2024). "The top three upregulated pathways associated with IGF2BP3 were as follows: pathogenic Escherichia coli infection, thyroid cancer and adherens junction." (PMID 33246429, 2020). "In thyroid cancer, it is rearranged with insulin-like growth factor 2 mRNA-binding protein 3 (IGF2BP3), and this fusion determines high expression of the IGF2BP3 protein, resulting in a deregulated activation of MAPK and PI3K signaling." (PMID 37761374, 2023). "In thyroid cancer cells, over expression of the IGF2BP3/IGF2 axis correlates with enhanced activation of the Akt and ERK pathways, increased cell proliferation and sensitivity to the dual inhibitor OSI-906." (PMID 33673232, 2021). "In approximately 5% of thyroid cancers, overexpression of insulin-like growth factor 2 binds to protein 3 (IGF2BP3) and low expression of IGF1R inhibit the abnormal growth of tumour cells caused by IGF2BP3." (PMID 34923978, 2021). "We showed that METTL14, FTO, and ALKBH5 were down-regulated in most cancers, whereas YTHDF1 and IGF2BP3 were up-regulated in 12 cancer types except for thyroid carcinoma (THCA)." (PMID 33718187, 2021). "In conclusion, the expression of SETMAR in thyroid cancer is stabilized by METTL3‐mediated m6A modification in an IGF2BP3‐dependent manner, which could explain its dysregulation during dedifferentiation of thyroid cancer." (PMID 38900084, 2024). "Moreover, only in thyroid carcinoma (THCA) IGF2BP3 had an increased expression in corresponding normal tissues instead of tumor samples, which was the opposite of the condition in other cancer types." (PMID 36761737, 2023). "IGF2BP3’s overexpression in thyroid carcinoma, its near undetectable levels in adult tissue, and its potential to distinguish between benign and malignant tissue make it an excellent candidate for the thyroid cancer sequencing panel." (PMID 28117295, 2017). "However, through the use of reverse transcription polymerase chain reaction (RT-PCR) and qRT-PCR assay, it was demonstrated that IGF2BP3 was overexpressed in thyroid carcinoma tissue when compared to benign thyroid lesions." (PMID 28117295, 2017). "In this study, we identified SETMAR as a differentiation‐related histone methylation modifier in thyroid cancer, and we found that its mRNA was stabilized by METTL3‐mediated m6A modification in an IGF2BP3‐dependent manner." (PMID 38900084, 2024). "We detect a number of recurrent fusions, such as those involving ANO3, RGS9, FUT5, CHI3L1, OR1D4, and LIPG in breast; IGF2 in colon; ETV1 in prostate; and IGF2BP3 and SIX2 in thyroid cancers." (PMID 32631391, 2020). "Overexpression of IGF2BP3 mRNA and protein increases IGF2 translation and IGF1 receptor (IGF1R) signaling through PI3K and MAPK cascade reaction and promotes proliferation, invasion, and transformation of thyroid cancer cells." (PMID 33796449, 2021). "Similarly, IGF2BP3 binds the IGF2 3′-UTR, thus promoting its translation, increasing activation of IGF signaling and cell proliferation in leukemia, thyroid cancer and glioma." (PMID 33673232, 2021). "Although its role in thyroid cancer is unknown, it is noteworthy that THADA-IGF2BP3UIB consistently activates not only IGF2BP3 but also SIX2." (PMID 32631391, 2020). "By contrast, somatic mutations of TCF12, KDM5C, IGF2BP3 and MAP4K3 have not been reported in any types of thyroid cancers." (PMID 27626165, 2016).
renal cell carcinoma (12 papers, 2020 to 2025). "IGF2BP3 has been shown to be a prognostic and diagnostic biomarker and therapeutic target for renal cell carcinoma." (PMID 36520532, 2023). "A recent study found that the circRARS/IGF2BP3 complex enhances m6A recognition on specific genes, thereby regulating lipid metabolism to foster sunitinib resistance in renal cell carcinoma." (PMID 39988592, 2025). "IGF2BP3 silencing decreased HMGA1 protein levels accordingly in PTBP3 overexpressing renal cell carcinoma cells." (PMID 38405614, 2024). "The IGF2BP3/lncRNA CDKN2B-AS1/NUF2 axis promotes renal cell carcinoma cell growth and metastasis in vitro and in vivo." (PMID 37298373, 2023). "The high expression of IGF2BP3 indicates the metastasis and poor prognosis of renal cell carcinoma RCC." (PMID 35047058, 2022). "Patients with higher expression of IGF2BP3 showed longer metastasis-free survival and overall survival in renal-cell carcinoma." (PMID 32710725, 2020). "IGF2BP3 can be used to identify patients with early diagnosis of RCC renal cell carcinoma." (PMID 35047058, 2022). "High IGF2BP3 expression predicts metastasis formation and poor survival in renal cell carcinoma." (PMID 33094561, 2020). "Another study on renal cell carcinoma (RCC) revealed a different pathway, where IGF2BP3 stabilizes AGAP2-AS1, allowing it to competitively bind with miR-9-5p, consequently upregulating the expression of Thrombospondin-2 (THBS2) and activating the PI3K/AKT signaling pathway." (PMID 39521940, 2024). "It has been reported that overexpression of IGF2BP3 increased phosphorylation of IκBα and knockdown of IGF2BP3 reduced activation of IκBα in renal cell carcinoma (RCC) cells, indicating that IGF2BP3 activates the NF‐κB signalling pathway and promotes RCC cell migration and invasion." (PMID 33094561, 2020). "We show here that IGF2BP3 is induced in various animal models and human CKD, which is localized in the cytoplasm of tubular epithelial cells, consistent with previous studies in renal cell carcinoma." (PMID 36520532, 2023).
acute myeloid leukemia (11 papers, 2021 to 2025). Acute myeloid leukemia (AML) is a group of neoplasms arising from precursor cells committed to the myeloid cell-line differentiation. "In acute myelogenous leukemia, IGF2BP3 was observed to enhance the stability of RCC2 mRNA by reading m6A modification sites, thereby promoting cancer progression." (PMID 37298373, 2023). "Interestingly, an interaction between YB-1 and IGF2BP3 in primary human and mouse acute myeloid leukemia cells was recently reported." (PMID 34469566, 2021). "Additionally, IGF2BP3 stimulates tumorigenesis by RCC2 in acute myeloid leukemia." (PMID 38355626, 2024). "IGF2BP3 enhances the stability of RCC2 mRNA by reading the m6A modification sites, thereby reducing AML cell apoptosis and promoting the progression of acute myeloid leukemia." (PMID 37298373, 2023). "IGF2BP2 and IGF2BP3 augmented the stability of DDX21 mRNA in an m6A-dependent manner, followed by recruitment of transcription factor YBX1 by DDX21 on ULK1 gene promoter and elevated transcription of ULK1, which facilitates progression of acute myeloid leukemia." (PMID 39866844, 2025).
clear cell renal cell carcinoma (11 papers, 2021 to 2025). "Existing studies have directly elucidated the role of IGF2BP3 in clear cell renal cell carcinoma (KIRC)." (PMID 41589308, 2025). "We constructed a multi-gene risk prediction model incorporating IGF2BP3, CENPA, and MEF2B to evaluate the prognostic predictive power of these three key genes in clear cell renal cell carcinoma (KIRC)." (PMID 41589308, 2025). "A study has revealed that IGF2BP3 stabilized CDKN2B-AS1 to promote the progression of renal clear cell carcinoma via epigenetically activating NUF2 transcription." (PMID 37106446, 2023). "In clear cell renal cell carcinoma, the complex of IGF2BP3/lncRNA DMDRMR selectively interacts with their m6A-modified co-targets (including CDK4, COL6A1, LAMA5, and FN1) to promote cell proliferation." (PMID 37280679, 2023). "In clear cell renal cell carcinoma, IGF2BP3 suppresses cancer sensitivity to CDK4/6 inhibitor palbociclib by stabilizing CDK4 mRNA in an m6A- dependent manner." (PMID 37280679, 2023). "For instance, IGF2BP3 enhanced the proliferative activity of clear cell renal cell cancer cells by increasing the expression of cyclin-dependent kinase 4, collagen type VI alpha 1 chain, laminin subunit alpha 5, and fibronectin 1 in an m6A-dependent manner." (PMID 34621671, 2021). "Similarly, the upregulation of the m6A reader IGF2BP3 has been identified as a new biomarker of many cancers; for instance, the co-expression of IGF2BP3 and the lncRNA DDRMR is a diagnostic and prognostic marker in clear cell renal cell carcinoma (ccRCC)." (PMID 37965577, 2023). "LncRNA CDKN2B-AS1 was stabilized by IGF2BP3, recruited CBP and SMYD3 and activated NUF2 transcription in renal clear cell carcinoma." (PMID 35676262, 2022). "Consistently, in clear cell renal cell carcinoma, lncRNA DMDRMR bound IGF2BP3 to stabilize CDK4 and three extracellular matrix components (COL6A1, LAMA5, and FN1) by specifically enhancing IGF2BP3 activity in a m6A-dependent manner." (PMID 35676262, 2022).